BRCA2 (BRCA2 DNA repair associated)
Diseases named in the same sentence as BRCA2 in open-access papers (continued):
Sharing a sentence is not in itself a finding about the gene and the disease.
tumor (continued). "Deleterious alterations in DDR genes associated with increased sensitivity to PARP inhibitors in other tumor types (e.g. BRCA1, BRCA2, PALB2, RAD51C and RAD51D) were infrequent (9.4%) in ATLAS." (PMID 34030643, 2021). "In recent decade, many tumor-suppressor genes such as BRCA1, BRCA2 and BLM and downstream nucleases including XPF and MRE11 have been suggested as proteins that are important for R-loop tolerance and removal." (PMID 33857133, 2021). "To date, intensive efforts have been devoted to understanding the tumor-suppressive functions of BRCA1–BARD1 and BRCA2 in mitotic cells." (PMID 33593852, 2021). "Twenty-two FA-related genes have been identified including tumor suppressors BRCA1 (FANCS) and BRCA2 (FANCD1)." (PMID 34504103, 2021). "The CNV patterns were analogous to, but distinct from, those in the BRCA2 germ line carrier PS13-9062 with variable shared and unique CNVs across the sorted populations in each tumor." (PMID 34011996, 2021). "While it is well established that the tumor suppressors BRCA1 and BRCA2 function in DNA repair and homologous recombination in somatic cells, the functions of BRCA1 and BRCA2 in meiosis have received less attention." (PMID 33996823, 2021). "If TEs insert into DNA repair genes such as breast cancer type 2 susceptibility protein (BRCA2) or tumor suppressor genes such as adenomatous polyposis coli protein (APC) and retinoblastoma protein 1 (RB1), they may cause genome instability or tumor formation, respectively." (PMID 34364371, 2021). "Gene alterations in BRCA1, BRCA2, and ATM were detected in 2.0, 10.7, and 8.8%, respectively, of cfDNA samples and in 1.6, 8.2, and 5.8%, respectively, of tumour tissue samples." (PMID 33630412, 2021). "The RNAseq data showed that the median frequency of DMD alterations in non-myogenic tumours (3.4%) was higher than that in other common tumour suppressor genes, such as BRCA1 (1.6%), BRCA2 (2.8%) and PTEN (3%)." (PMID 33188621, 2021). "Second, tumor-only sequencing was performed, and it was difficult to differentiate somatic mutations from those with germline origin, which might hinder the clinical applicability, particularly for PARP inhibitors, as germline mutation of BRCA1 or BRCA2 is the prerequisite for synthetic lethality." (PMID 34203389, 2021). "The median relative expression of BRCA2 was 1.04 in paracancerous tissues and 0.46 in ESCC tissues, which was significantly decreased in tumor tissues (Wilcox test, P = 0.041)." (PMID 34722771, 2021). "Mice carrying DLD1 WT or BRCA2−/− tumors were treated with either NSC617145 or drug vehicle alone and relative tumor growth was monitored over time." (PMID 34772932, 2021). "Of 64 patients with data from tumor tissue samples, 10 (15.6%) had a deleterious alteration in a DNA damage repair pathway gene, including four with a deleterious BRCA1 or BRCA2 alteration." (PMID 34030643, 2021). "In germline BRCA1/BRCA2/RAD51C/RAD51D/BRIP1 PVs, 44.4% (24/54) had a positive FH compared to 11.3% (28/249) of sporadic tumours (p < 0.001)." (PMID 34503154, 2021). "Somatic BRCA1 or BRCA2 mutation carriers were identified with bidirectional sequencing of DNA from archived tumor tissue, if the test could not be performed due to technical reasons from tumor cells, the sequencing was done from peripheral blood cells to identify germline mutation carriers." (PMID 33478135, 2021).
tumor (continued). "A large number of proteins are critical for HR, including the tumor suppressors BRCA1 and BRCA2, whose functions have been well characterized in somatic cells in the context of DNA damage and carcinogenesis." (PMID 33996823, 2021). "Many mouse models have been generated to study the function of BRCA1, BRCA2, and PALB2 in development and tumor suppression." (PMID 33893322, 2021). "The tumour material from all of the 274 patients underwent sequencing for the BRCA1 and BRCA2 genes." (PMID 34680387, 2021). "The expression of 51 genes was able to accurately segregate the three tumour genotypes (BRCA1, BRCA2 and sporadic)." (PMID 33081408, 2020). "It is well known that the tumor suppressor genes BRCA1 and BRCA2 play a critical role in homologous recombination, which is considered to be the major mechanism for genome integrity in the process of cell proliferation." (PMID 32879886, 2020). "The distribution of the tumor characteristics of BRCA1 and BRCA2 carriers agreed with previous reports, so that small, high-grade, and early-onset tumors had a relatively high frequency." (PMID 32964118, 2020). "In this study, BRCA2 mutated tumors were, similar to ERCC2 mutated tumors, associated with high numbers of mutations in a SBS5 context, indicating that this mutational signature is an indicator of a DDR-deficient tumor that may be more sensitive to chemotherapy." (PMID 32978382, 2020). "In the current study, we found that the five differential expression genes (NFBD1, BRCA1, BRCA2, RPA1 and RAD51) were involved in NPC radioresistance, which was further validated in CNE2-RR cells, tumor xenografs and NPC patients." (PMID 32015678, 2020). "The lack of positive findings in the BRCA2-specific analyses prompted us to consider the possibility that there may be confounding factors, so that the genetic survival associations would depend on tumor and patient characteristics." (PMID 32964118, 2020). "Germline and acquired BRCA1 and BRCA2 alterations represent the most typical genetic alterations that determine a condition of HRD, leading to the inactivation of these tumor suppressors." (PMID 32210163, 2020). "First tested in vitro, thedrug selectively targeted tumor cells with BRCA1,BRCA2, or PTEN gene alterations with 20-to more than 200-fold greater potency than existing PARP1/2 inhibitors (such asolaparib, rucaparib, and veliparib) (Shenet al., 2013)." (PMID 31067289, 2019). "This is indicative of a bigger awareness in terms of preventive diagnosis for this tumor type, especially following the publicity received by the BRCA1 and BRCA2 genes due to the “Jolie effect”." (PMID 31159747, 2019). "Tumor accumulation of thorium-227 was observed out to 336 h, with a measured uptake of 42 ± 4% and 59 ± 10% injected activity per gram (% IA/g) tumor for the DLD-1 parental and DLD-1 BRCA2 -/- respectively." (PMID 31618864, 2019).
tumor (continued). "We defined 5 HGSC groups, representing BRCA1-mutant (clusters 1, 10; n = 36), BRCA2-mutant (cluster 4, n = 19), FBI (clusters 2, 5, 7; n = 50), Intra-Chr (cluster 8, n = 8), and CDK12-like tandem duplicator tumours (cluster 11, n = 5)." (PMID 30794536, 2019). "The joint role of BRCA1 and BRCA2 in HR is thought to explain their common disease phenotype, but BRCA1 also has tumor-suppressive effects through other functions." (PMID 31683985, 2019). "Recently, Illumina Inc. offered the TruSight Tumor 170 panel targeting 170 genes including BRCA1 and BRCA2." (PMID 31029168, 2019). "Almost half of recurrent IDHWT tumours (43%; 3/7) harboured at least one potentially actionable variation in the genes EGFR (14%; 1/7), PTEN (14%; 1/7), BRCA1 (14%; 1/7), BRCA2 (14%; 1/7), and ATM (14%; 1/7)." (PMID 32082376, 2019). "ER status was also the only independent tumor characteristic that distinguished between BRCA1 and BRCA2 carriers (ORBRCA2 vs BRCA1: 0.22 [0.07–0.77])." (PMID 30175445, 2019). "Tumor accumulation of the HER2-TTC over time was accompanied by a decrease of thorium-227 in blood, with a tumor to blood ratio at 336 h of 17.3 ± 3.5 for the DLD-1 parental and 12.8 ± 2.4 for the DLD-1 BRCA2 -/-." (PMID 31618864, 2019). "To determine the level of tumor-infiltrating immune cells, we examined CD3+ T cells and F4/80+ macrophages in tumors from KPC, Palb2-KPC, Brca1-KPC, and Brca2-KPC animals." (PMID 31877165, 2019). "Grade 3 was the most common tumor grade in BRCA1 tumors (65%), followed by BRCA2 (44%) tumors, compared to only 27% of BRCA WT tumors (p < 0.001, p = 0.006, respectively)." (PMID 31307407, 2019). "The tumor size of most of the tumors in all of the three groups (45% of BRCA1, 53% of BRCA2, and 63% of WT tumors) was < 2 cm." (PMID 31307407, 2019). "For BRCA2 versus BRCA1 tumors, univariate analysis showed that tumor grade, ER, PR, HER2, CK5, CK14, and CLDN3 were independent parameters of BRCA2 status." (PMID 31307407, 2019). "Other possible signatures of recurrent tumour resistance in this GBM cohort included CNV gains in the genes (chromosome), BRCA2 (Chr13), GNAS (Guanine nucleotide-binding protein G(s) subunit alpha; Chr20), and EGFR (Chr7)." (PMID 32082376, 2019). "The preliminary results of the phase II trial TRITON2 evaluating the efficacy of rucaparib in a preselected population with DDR defects in tumor or ctDNA showed PSA and radiographic responses in 48% and 45% of patients harboring BRCA2 defects." (PMID 30871108, 2019). "For sample 36, there appears to be a hemizygous deletion in BRCA2 in the initial, but a CNV gain in the recurrent tumour." (PMID 32082376, 2019). "Xenograft tumours were subsequently established from BRCA2+/+ and BRCA2−/− HCT116 cells and assessed for their response to chlorambucil, cisplatin and talazoparib." (PMID 31273933, 2019). "Whilst I'm not aware that this has been studied extensively in germ line tumours, SYCP3 does become expressed in germ line tumours, so disruption of BRCA2 activity in germ line tumours by meiotic factors is an interesting possibility." (PMID 31102330, 2019). "Under normal conditions, PALB2 functions as a tumor suppressor similarly to BRCA1 and BRCA2 in maintaining the genome stability and cellular homeostasis." (PMID 29643976, 2018). "Other tumor suppressor genes, such as WT1, SMAD4, and BRCA2, which are also silenced in all samples, are frequently associated to polycomb-repressed (E15, H3K27me3) or heterochromatin-like (E12, H3K9me3) states." (PMID 29773832, 2018).
tumor (continued). "A small fraction of intracellular BRCA2 binds physically with BRCA1, consistent with evidence that these tumor-suppressor proteins share at least certain biological functions during the cellular response to DNA damage." (PMID 29386125, 2018). "DNA was extracted from formalin-fixed paraffin-embedded (FFPE) archival tumour material and sequenced using the Ion Ampliseq BRCA1 and BRCA2 panel." (PMID 29298688, 2018). "Methylation profiling of FBC was able to discriminate BRCA1, BRCA2 and two subsets of BRCAX tumours." (PMID 28893223, 2017). "In our study, carboplatin inhibits tumor cells through inducing DNA damage, and curcumin-induced decreases in BRCA1 and BRCA2 expression contribute to carboplatin’s cytotoxic effect." (PMID 29255221, 2017). "Of note, the tumor-promoting effects of USP21 are likely to go beyond the modulation of HR and/or BRCA2 stability, as BRCA2 overexpression was unable to fully restore HCC tumor cell growth." (PMID 28743957, 2017). "Locus-specific LOH, which can be determined from already existing DNA-based FFPE tumor testing pipelines remains a clinically promising and more cost-effective means of predicting therapy response in germline BRCA1 and BRCA2 carriers." (PMID 28831036, 2017). "Biochemical dissection suggests that USP21 can associate with the C-terminal OB domains of BRCA2, and consistent with this, a tumor cell line with a C-terminal BRCA2 truncation is unresponsive to USP21 depletion with regard to BRCA2 stability and tumor growth." (PMID 28743957, 2017). "We also observed that patients with predicted biallelic inactivation of BRCA1 or BRCA2 had higher BRCA-like signature activity in both cfDNA and tumor biopsies (Wilcoxon rank-sum test, one-tailed, p < 0.01)." (PMID 29109393, 2017). "USP21 stabilizes BRCA2 in patient-derived HCC tumor cell lines, protects from DNA damage and promotes tumor cell growth in a BRCA2-dependent manner." (PMID 28743957, 2017). "However, in three cases, tentative explanations exist for the absence of tumour in MRI images: for the patient with a BRCA2 mutation, the extended 5 months period between imaging and surgery may explain the lack of detection." (PMID 28705168, 2017). "Copy number analysis based on exome sequencing data using VarScan software showed that the genome area hosting ATM, BRCA2 and CCND2 genes had >2-fold intensity changes in all three paired tumor samples compared to matched normal tissue samples." (PMID 28423512, 2017). "This suggests that simultaneous inhibition of BRCA2 and PARP-1 in heterogeneous tumor populations can prevent selection events and forestall emergence of treatment-resistant clones." (PMID 26959114, 2016). "We conclude that not only are BRCA2 and PALB2 required for tumor suppression, their physical interaction is equally important." (PMID 27490902, 2016). "A subset of FA proteins includes the well‐characterised RAD51 recombinase, as well as the tumour suppressors BRCA1 and BRCA2, which are directly involved in the homologous recombination (HR) pathway of double‐strand break (DSB) repair." (PMID 27037238, 2016). "Substantial crosstalk between the two pathways has recently been unravelled, in that key HR proteins such as the RAD51 recombinase and the tumour suppressors BRCA1 and BRCA2 also play important roles in ICL repair." (PMID 27037238, 2016). "In this regard, about 15% of our samples showed a complete deletion of the BRCA1 or BRCA2 genes, suggesting that LOH represents the most common event in tumor cells." (PMID 27793035, 2016).
tumor (continued). "However, tumours in BRCA1 mutation carriers were more likely to present with more advanced stage (42.9 % vs. 23.5 %, P for trend = 0.11) and were more frequently ER− (9.7 % vs. 3.3 %, P = 0.17) and PR− (21.4 % vs. 13.2 %, P = 0.27) than tumours in BRCA2 mutation carriers." (PMID 26857456, 2016). "This suggests that simultaneous inhibition of both BRCA2 and PARP1 can prevent the outgrowth of resistant cells in a tumor population with HHR heterogeneity." (PMID 26959114, 2016). "The BCCIP (BRCA2- and CDKN1A-interacting protein) is an important cofactor for BRCA2 in tumor suppression." (PMID 27535137, 2016). "Among them, LOH in tumor was identified in 11 (61.1%) BRCA1 carriers and 13 (59.1%) BRCA2 carriers, respectively." (PMID 27257965, 2016). "Taken together, these observations have raised concerns over the significance of the interaction between BRCA2 and PALB2, especially on the tumor suppressor function of BRCA2." (PMID 27490902, 2016). "However, the use of a tumor sample for molecular analysis and further mutational analysis of the entire coding sequence of both BRCA1 and BRCA2 may significantly increase the total number of patients who may potentially benefit from targeted therapies with PARP inhibitors." (PMID 27167707, 2016). "We show that this method can detect BRCA1, BRCA2, ERBB2 and CCNE1 copy number changes in DNA extracted from snap-frozen and FFPE tumour tissue, with 100% sensitivity and >99.5% specificity." (PMID 26569395, 2015). "In the reproducibility experiments, three different samples (blood, FFPE tumour and snap-frozen tumour) with known germline exonic BRCA1 or BRCA2 gene deletions or duplications were prepared in triplicates by three different operators." (PMID 26569395, 2015). "Finally, the analysis of rs2426618 by ERα tumor status in BRCA2 mutation carriers did not reveal specific associations: ERα-positive, per-allele HR = 1.10, 95% CI 1.02–1.17, p = 0.010; ERα-negative, per-allele HR = 1.11,95% CI 0.97–1.26, p = 0.15, pdifference = 0.89." (PMID 25830658, 2015). "We also found higher expression of the NFκB-signalling TFs in BRCA1 tumours - the complex NFκB1-NFκB2-REL-RELA-RELB composed entirely of NFκB TFs, showed a higher correlation in BRCA1 tumours than BRCA2 tumours." (PMID 25521701, 2014). "We analyzed the ROC curves for all previously known potential factors, including age, tumor size, hemoglobin, along with our potential markers: BRCA1, BRCA2, RAD51, FANCD2, BLM and BRIP1." (PMID 24708616, 2014). "Of six tumour suppressor genes investigated BRCA1, BRCA2, and p14 appeared to be under strong epigenetic silencing." (PMID 24607238, 2014). "Olaparib (AZD2281) is a potent oral PARP inhibitor that has exhibited monotherapy activity in tumour cells with defective components of homologous recombination, including cells with the BRCA1−/− and BRCA2−/− genotype." (PMID 22223088, 2012). "We find that a BRCA2 fusion peptide deleted for the DNA binding domain and active in HR is completely dependent on interaction with the PALB2 tumor suppressor for activity." (PMID 22194698, 2011). "Together, these differences in tumor profiles suggest that BRCA1 and BRCA2 have different functions in DNA repair pathways, however, we have not been able to identify the nature of this difference using our aCGH profiles." (PMID 20735817, 2010). "Surprisingly, that study also showed that let-7 represses several tumour suppressor genes (BRCA1, BRCA2, FANCD2, and PLAGL1, among others) and checkpoint regulators (CHEK1, BUB1, BUB1B, MAD2L1, and CDC23, among others)." (PMID 20179807, 2010).